ENSG00000288695 (novel protein, SRD5A3-RP11-177J6.1 readthrough)
Gene: Protein-coding gene on chromosome 4 (55,346,228 to 55,388,368, forward strand). Ensembl gene ENSG00000288695.
Genetic constraint (gnomAD): Loss-of-function variants: 18 observed, 20.14 expected, observed/expected ratio (o/e) 0.89, 90% interval 0.62 to 1.33. Missense variants: 224 observed, 218.24 expected, observed/expected ratio (o/e) 1.03, 90% interval 0.92 to 1.15. Synonymous variants: 110 observed, 103.42 expected, observed/expected ratio (o/e) 1.06, 90% interval 0.91 to 1.25.